MUC5B (mucin 5B, oligomeric mucus/gel-forming)
Diseases named in the same sentence as MUC5B in open-access papers (continued):
Sharing a sentence is not in itself a finding about the gene and the disease.
cancer (47 papers, 2005 to 2026). A tumor composed of atypical neoplastic, often pleomorphic cells that invade other tissues. "MUC5B, a member of the mucin family, has been implicated in the initiation or progression of several cancers including lung cancer." (PMID 29670111, 2018). "Inversely, MUC5B expression causes a more malignant phenotype in several cancers." (PMID 36831639, 2023). "A comprehensive RNA-Seq analysis revealed significant mRNA upregulation of several genes, including ACTA1, IGFBP2, MUC5B, CEACAM5, and KRT19, all of which are associated with cancer progression in various types of malignancies (p < 10−10)." (PMID 40004774, 2025). "We observed bimodal gene expression in columnar-like and squamous-like cancers, including MUC5B, KRT5 and CSTA, that differentiates ADC from SCC." (PMID 33462395, 2021). "MKN45 and KATO III cell lines have high MUC5B expression, and MUC5B plays a role in cancer cell resistance to chemotherapeutic drugs." (PMID 32825724, 2020). "Further studies investigated the effect of this abnormal expression of the MUC5B gene on the biological behavior of different types of cancers." (PMID 32695780, 2020). "Moreover, researchers have found that mutations in MUC5B are positively correlated with immune cells in the TME, such as cancer-associated fibroblasts and myeloid-derived suppressor cells." (PMID 40655139, 2025). "We used cancer-derived A549 airway epithelial cells to interrogate the activity of this reporter in comparison with a construct spanning approximately 5 kb upstream of the MUC5B start site through the native promoter (Long)." (PMID 33320836, 2021). "MUC5B, another gel-forming mucin, was identified to be up-regulated in all four cancer types." (PMID 33947930, 2021). "Those CNC variations associated with poor outcome (MUC5B, ZXDB, PLIN4, CCDC144NL, CNTNAP3B, and CCDC180) may probably facilitate cancer initiation and progression, and may be a new clue to study cancer metastasis and evolution." (PMID 29262625, 2017). "Missense mutations were noticed in all genes except CALML3 and IL1B.On the other hand methylation of hub genes were depicted in in which CCR9 and MUC5B were hypermethylated in CESC which can lead to gene silencing and promote metastasis of cancer." (PMID 40653567, 2025). "Similar to a previous ST study, we observed the high expression of mucin family genes in cancer cells, such as MUC16, MUC4, and MUC5B." (PMID 37124494, 2023). "While we were most interested in the cancerous squamous epithelial cells, the number of CECs (MUC5B, WFDC2) was larger than that of the cancer cells (TP63, KRT5, CDKN2A)." (PMID 35986392, 2022). "Many other cancer-related genes showed up differentially expressed in PDAC, including MUC2, MUC5B, MUC13, ALDH3A1, CDCA7, and CCL2." (PMID 31379917, 2019). "For the 19 Mucin (MUC) family genes, nine of them were RMGs and four of them (MUC17, MUC5B, MUC4, and MUC16) were common RMGs shared in 8 to 17 cancer types." (PMID 30107644, 2018). "By determining expressions of the three MUCs in additional 68 pairs of samples, we confirmed the upregulations of MUC5AC and MUC5B but not MUC3A in cancer tissues." (PMID 37324942, 2023). "Healthy human pancreas ducts are reported to have MUC5B expression and lack MUC5AC expression, but both may be present in diseased pancreas (e.g. cancer)." (PMID 37349833, 2023). "Additional variants, including MUC5B, DNAH11, ANK2, and LAMA5, which were not part of tier-1 genes but has been reported in other gastrointestinal patients (according to the Cancer Browser) were also consistently detected." (PMID 37878600, 2023). "The expression of the MUC5B gene has been reported to be a specific mechanism used by cancer cells to maintain a non-differentiating state." (PMID 35572847, 2021). "Surprisingly, patients with MUC3A, MUC4, MUC5B, MUC6, and MUC16 mutations had significantly better OS prognoses compared with those without mutations in several cancer types." (PMID 30107644, 2018).
cancer (continued). "Saliva from the cancer patients showed a low abundance/no detectable MUC7, while the MUC5B level remained, compared to saliva from a healthy control." (PMID 34627217, 2021).
bacterial infection (12 papers, 2014 to 2025). "Consistently, loss-of-function models and human cases with deficient MUC5B exhibit recurrent bacterial infections, impaired mucociliary clearance, and granulocytic accumulation, underscoring its role in airway defense and immune homeostasis." (PMID 41561092, 2025). "A major constituent of mucus are polymeric mucin glycoproteins (e.g., Muc5b and Muc5ac) that can directly interact with immune cells as evident by the fact that Muc5b-deficient mice are susceptible to bacterial infection due to impaired MΦ responses." (PMID 35834490, 2022). "The MUC5B gene is conserved in the mouse genome, allowing the generation of a Muc5b-deficient mouse strain showing that Muc5b is important for mucociliary clearance in the lung during bacterial infection." (PMID 28355261, 2017). "MUC5B is a high-molecular glycoprotein secreted by the bronchial glands and is required for airway defense and controlling bacterial infection." (PMID 37770976, 2023). "At thesame time, increased barrier properties of MUC5B contaminated gastricmucus toward small, charged molecules could constitute a challengefor the therapeutic treatment of such bacterial infections." (PMID 40021478, 2025). "MCC is decreased in MUC5B−/− mice, but not in MUC5AC−/− mice and the MUC5B−/− mice are more susceptible to bacterial infection." (PMID 37049536, 2023). "Furthermore, Muc5b defect increases the accumulation of pathogens in mice respiratory tract, which leads to chronic bacterial infection and hardly dissolved inflammation." (PMID 35292003, 2022). "Mucin 5B has been shown to be required for respiratory tract health, and muc5b−/− mice exhibit severe morbidity and mortality due to an inability to clear routine debris (e.g., hair), leading to persistent bacterial infection of the lungs." (PMID 25333937, 2014). "Previous animal experiments have proved that airway secreted mucin MUC5B but not Mucin 5AC (MUC5AC) plays a critical role in immune defense against bacterial infections." (PMID 35292003, 2022).
respiratory diseases (8 papers, 2011 to 2024). "This is the first study reporting on the prevalence of the MUC5B minor T allele in chronic end-stage respiratory diseases and the association between this variant and post-transplant outcome." (PMID 35651878, 2022). "In the present study, MAF of the MUC5B promoter polymorphism was significantly higher in ILD than in other end-stage respiratory diseases." (PMID 35651878, 2022). "A nonsense variant, MUC5B:c.16861G > T, p.Glu5621*, was found in homozygous state in two siblings with severe respiratory disease from birth." (PMID 33526882, 2021). "Two missense variants, MUC5B:c.14936 T > C, p.Ile4979Thr (rs201287218) and MUC5B:c.16738G > A, p.Gly5580Arg (rs776709402), were also found in compound heterozygous state in two siblings with severe respiratory disease from birth." (PMID 33526882, 2021). "The results here show significant respiratory diseases associated with likely pathologic variants, such as ABCA3:p.Val1399Met, MUC5B:p.Ile4979Thr, MUC5B:p.Gly5580Arg, MUC5B:p.Glu5621*, SCNN1B:p.Arg206Trp, SCNN1B:p.Glu468Lys, and SFTPA1:p.Gly98Ala." (PMID 33526882, 2021). "In humans, the congenital absence of MUC5B recently defined a new category of genetic respiratory disease associated with sinus disease, impaired mucociliary clearance, and lung function impairment." (PMID 39769414, 2024). "The MUC5B promoter polymorphism was only associated with ILD as the MAF of the MUC5B polymorphism in the non-ILD end-stage respiratory diseases was comparable to the reported 9% in the normal Caucasian population." (PMID 35651878, 2022).
adenocarcinoma (7 papers, 2013 to 2025). A common cancer characterized by the presence of malignant glandular cells. "The diagnostic accuracies of TTF-1 and MUC5B for adenocarcinoma were 83.8% and 70.4%, respectively." (PMID 25733373, 2015). "Consistent with this, we found that the adenocarcinoma marker, MUC5B, was downregulated in A3B-on GRB and GRF cells." (PMID 40323013, 2025). "Conversely, NKX2-1 and mucins (MUC1, MUC5B) were more highly expressed in adenocarcinoma, as were ROS1 and CLDN3." (PMID 32381040, 2020). "MUC5B expression was significantly associated with poorer differentiation (P = 0.0303), higher pathological TNM stage (p = 0.0153) and poorer prognosis of adenocarcinoma patients (P = 0.0017)." (PMID 25733373, 2015). "We also immunohistochemically evaluated TTF-1 expression and found that the combination of MUC5B with TTF-1 is a useful marker for adenocarcinomas." (PMID 25733373, 2015).
inflammation (3 papers, 2017 to 2022). Aberrant reaction of the microcirculation characterized by movement of fluid and leukocytes from the blood into extravascular tissues. "In the present study, we demonstrated that the transcript levels for muc1, muc2, muc3, muc4, muc5b and muc13 in lung tissue were unaltered, whereas muc5ac transcript expression was significantly increased during allergen-induced airway inflammation in mice." (PMID 28205598, 2017). "Chronic airway inflammation in βENaC-Tg mice is associated with mucus hypersecretion, as evidenced by goblet cell metaplasia and elevated expression of secreted mucins (MUC5AC and MUC5B) that were found to be reduced in βENaC-Tg mice that lack NE (βENaC-Tg/NE-/-)." (PMID 36362203, 2022).
lung (2 papers, 2013 to 2018). "Nevertheless, we observed that genes such as DNAH6, MUC5B, HELZ2, and KIAA0100 were frequently mutated in three of six lung ACC metastases." (PMID 30301885, 2018).
cardiac disease (1 paper, 2016). "Among these 4 genes, TTN was the most likely cardiac disease associated gene while lack of evidence for NPHP3, DNAI1, and MUC5B genes existed." (PMID 28018021, 2016).
MUC5B also shares sentences with these, for which no sentence is quoted: melanoma (6 papers); systemic sclerosis (4); bronchiectasis (3); lung squamous cell carcinoma (3); Alzheimer disease (2); asbestosis (2); autoimmune disease (2); chronic sinusitis (2); connective tissue disease (2); glioblastoma (2); intestinal disease (2); meningioma (2); myositis (2); sarcoma (2); allergic rhinitis (1); Barrett esophagus (1); bladder carcinoma (1); breast adenocarcinoma (1); bronchitis (1); cholangitis (1); chronic gastritis (1); chronic kidney disease (1); chronic lung disease (1); co-infection (1); duodenal adenocarcinoma (1); endothelial dysfunction (1); experimental autoimmune encephalomyelitis (1); fibrosarcoma (1); gallbladder cancer (1); gallstones (1).
A further 34 diseases each share a sentence with MUC5B in 1 paper.